SRSF3 (serine and arginine rich splicing factor 3)
Description:
Splicing factor, which binds the consensus motif 5'-C[ACU][AU]C[ACU][AC]C-3' within pre-mRNA and promotes specific exons inclusion during alternative splicing. Interaction with YTHDC1, a RNA-binding protein that recognizes and binds N6-methyladenosine (m6A)- containing RNAs, promotes recruitment of SRSF3 to its mRNA-binding elements adjacent to m6A sites within exons. Also functions as an adapter involved in mRNA nuclear export. Binds mRNA which is thought to be transferred to the NXF1-NXT1 heterodimer for export (TAP/NXF1 pathway); enhances NXF1-NXT1 RNA-binding activity. Involved in nuclear export of m6A-containing mRNAs via interaction with YTHDC1: interaction with YTHDC1 facilitates m6A-containing mRNA-binding to both SRSF3 and NXF1, promoting mRNA nuclear export.
Synonyms: SFRS3; SRP20
Tractability: PROTAC: ubiquitination databases record sites on it; its protein half-life has been measured.
Gene: Protein-coding gene on chromosome 6 (36,593,787 to 36,605,911, forward strand). Ensembl gene ENSG00000112081.
Subcellular location: Nucleus; Nucleus speckle; Cytoplasm
Subcellular location (Human Protein Atlas): Nucleoplasm
Pathways (Reactome):
Metabolism of RNA: Processing of Capped Intron-Containing Pre-mRNA; Transport of Mature mRNA derived from an Intron-Containing Transcript; mRNA 3'-end processing; mRNA Polyadenylation; mRNA Splicing - Major Pathway
Disease: Dengue Virus-Host Interactions
Gene Ontology:
Molecular function: pre-mRNA binding; primary miRNA binding; protein binding; protein-RNA sequence-specific adaptor activity; RNA binding; nucleic acid binding; phospholipase binding; sequence-specific mRNA binding
Biological process: mRNA export from nucleus; primary miRNA processing; regulation of mRNA splicing, via spliceosome; regulation of alternative mRNA splicing, via spliceosome; RNA processing
Cellular component: nuclear speck; nucleoplasm; cytoplasm; nucleus
Genetic constraint (gnomAD): Loss-of-function variants: 0 observed, 20.55 expected, observed/expected ratio (o/e) 0, 90% interval 0 to 0.14. The upper end of that interval is the gene's LOEUF score, 0.14, which puts it in group 1 of 6, group 1 being the genes least tolerant of losing a copy. Missense variants: 58 observed, 222.77 expected, observed/expected ratio (o/e) 0.26, 90% interval 0.21 to 0.32. Synonymous variants: 87 observed, 75.46 expected, observed/expected ratio (o/e) 1.15, 90% interval 0.97 to 1.38.
Homologues: Orthologues: chimpanzee SRSF3 (100% identical), dog SRSF3 (100% identical), guinea pig SRSF3 (100% identical), mouse Srsf3 (100% identical), pig SRSF3 (100% identical), rabbit SRSF3 (100% identical), rat Srsf3 (100% identical), tropical clawed frog srsf3 (97% identical), zebrafish srsf3b (94% identical), zebrafish srsf3a (90% identical), macaque SRSF3 (72% identical), Drosophila melanogaster x16 (60% identical), and 2 more. Paralogues in human: SRSF7 (65% identical), SRSF1 (48% identical), SRSF4 (47% identical), SRSF6 (46% identical), SRSF5 (40% identical), SRSF9 (38% identical), RSRC2 (29% identical), RSRP1 (25% identical).
Diseases named in the same sentence as SRSF3 in open-access papers:
SRSF3 is named in the same sentence as 93 diseases in open-access papers, as found by Europe PMC text mining. Sharing a sentence is not in itself a finding about the gene and the disease. The quoted sentences say what the papers report.
breast carcinoma (32 papers, 2016 to 2025). "Here, we found four upregulated hub genes (RPSA, SEC61A1, ITGB1, PSMB5) and three downregulated hub genes (PSME3, SNRNP70, SRSF3) that are significantly associated with poor overall survival of breast cancer patients." (PMID 36293493, 2022). "The function of SRSF3 in Paclitaxel treatment in breast cancer is analyzed by gain-of-function or loss-of-function assay in the breast cancer cell line MCF-7." (PMID 34356101, 2021). "As a potential diagnostic and prognostic biomarker, SRSF3 is overexpressed in various types of cancer, including cancer of the breast, retinoblastoma, ovarian cancer, gastric cancer, head and neck cell squamous, colorectal cancer, cervical cancer and hepatocellular carcinoma (HCC)." (PMID 36251702, 2022). "In addition, SNRPD1/3 plays a regulatory role in breast cancer through cell cycle regulation, and SRSF3/7 is an RNA-binding protein associated with metastasis and recurrence." (PMID 36434140, 2022). "SRSF3 overexpression rescues the growth inhibition caused by Paclitaxel in breast cancer cells." (PMID 34356101, 2021). "Studies report that three SNPs in SRSF3 (rs2145048, rs1406945, and rs9394364) were found in breast cancer, which may be associated with susceptibility to cancer." (PMID 33072610, 2020). "Additionally, the oncogenic SRSF1 and SRSF3 are overexpressed in multiple human cancers, including lung, colon, and breast cancers, despite limited mutations of them have been revealed." (PMID 31065692, 2019). "We found by RNA-seq that Srsf3 KO promoted the exon 11 inclusion of Eif4a2 splicing and reduced Eif4a2 RNA level due to induction of Eif4a2 RNA degradation in breast cancer." (PMID 40568073, 2025). "We discovered Srsf3 plays an oncogenic role in breast cancer and Srsf3 knockout (KO) in mammary glands delays the development of breast cancer in an Erbb2 mouse model." (PMID 40568073, 2025). "Breast cancer tissues show increased SRSF3 expression, and the increased expression of SRSF3 was found to correlate with breast cancer progression and 5-year overall survival." (PMID 40568073, 2025). "We demonstrated that Srsf3 is oncogenic in breast cancer formation, but tumor-suppressive in liver cancer formation." (PMID 40568073, 2025). "Others, including Cox8a, Ndufb8, and Atad1, which are the genes involved in oxidative phosphorylation pathway, also exhibited an opposite regulation by Srsf3 KO in our Erbb2 breast cancer and DEN-induced liver cancer." (PMID 40568073, 2025). "Srsf3 KO inhibits expression of Mfsd4a and Eif4a2 in breast cancer but enhances Mfsd4a and Eif4a2 expression in liver cancer." (PMID 40568073, 2025). "Srsf3 KO was found to reduce Srsf1 protein expression both from the Erbb2 breast cancer and DEN-induced liver cancer." (PMID 40568073, 2025). "In the Erbb2 breast cancer, a total of 425 differentially expressed genes were identified, of which 159 genes were upregulated and 266 genes were downregulated in Srsf3 KO breast cancer when compared to WT Srsf3 breast cancer." (PMID 40568073, 2025). "We found that the gene expression profile from breast cancer affected by Srsf3 KO was very different from liver cancer affected by Srsf3 KO." (PMID 40568073, 2025). "This opposite response of Mfsd4a to Srsf3 KO from Erbb2 breast cancer to DEN-induced liver cancer was remarkable by IGV visualization of RNA-seq reads-coverage and easily validated by NanoString analysis." (PMID 40568073, 2025). "Consistently, we found conditional Srsf3 KO in mouse mammary glands prevent c-neu (Erbb2) expression and thus, Erbb2 breast cancer induction, providing for the first time the direct in vivo evidence of Srsf3’s oncogenic feature." (PMID 40568073, 2025). "The increased expression of SRSF3 in breast tumors tissues was found in correlation with breast cancer progression and 5-year overall survival." (PMID 40568073, 2025). "SRSF3 promotes the usage of proximal splice site of exon 9 and the product of GRα in breast cancer cells 138 or THP-1 cells." (PMID 37416784, 2023).
breast carcinoma (continued). "An antisense oligonucleotide blocking an exonic splicing suppressor in the exon 4 can significantly increase inclusion of the exon 4, leading to inhibit SRSF3 expression and suppress proliferation of oral squamous cell carcinoma 172 and breast cancer cells." (PMID 37416784, 2023). "In a mouse breast cancer cell line, Srsf3 knockdown significantly reduces cellular migration, invasion in vitro, and lung metastasis in vivo." (PMID 37416784, 2023). "In breast cancer cells, SRSF3, along with hnRNP H1, has been identified as a regulator responsible for controlling the production of distinct splice variants of ERBB2 with different functionalities." (PMID 37875914, 2023). "In a mouse model of mammary tumorigenesis, Srsf3 expression is dramatically up-regulated during the progress of mammary cancer in both mRNA and protein levels." (PMID 37416784, 2023). "The splicing factor SRSF3, which is the smallest member of the serine/arginine rich protein family, is a proto-oncogene OE in many cancers, including breast cancer, and is known to regulate cancer progression, metastasis, prognosis, and drug resistance." (PMID 35504883, 2022). "The in vitro experiments performed on both OSCC (CAL 27 and SCC-9) and breast cancer (MCF-7) cells revealed that Paclitaxel treatment decreased SRSF3 expression." (PMID 34356101, 2021). "For example, it was shown that serine/arginine-rich splicing factor 3 (SRSF3) promotes the progression of breast cancer but suppresses hepatic carcinogenesis." (PMID 32106418, 2020). "Srsf3 KO prevents the Erbb2 breast cancer induction but enhances DEN-induced liver carcinogenesis." (PMID 40568073, 2025). "We then investigated the tissue-specific KO of Srsf3 on cancer induction in two well-established mouse cancer models: activated rat c-neu (V664E) replacement of mouse Erbb2-induced breast cancer (Erbb2 breast cancer in this report), and DEN-induced liver cancer." (PMID 40568073, 2025). "In this report, we demonstrated that SRSF3 at its physiological level functions as a tumor-promotor in development of Erbb2 breast cancer, but a tumor-suppressor in DEN-induced liver cancer, through regulation of RNA transcription or alternative splicing of a different set of genes." (PMID 40568073, 2025). "These gene expression patterns exemplify how Srsf3 could act as a proto-oncogene in Erbb2 breast cancer, but a tumor suppressor in DEN-induced liver cancer." (PMID 40568073, 2025). "Moreover, we identified that 24 out of 41 genes responsive to Srsf3 KO exhibited opposite expression profiles between breast cancer and liver cancer." (PMID 40568073, 2025). "Altogether, the altered gene expression and alternative RNA splicing by Srsf3 KO in mouse mammary glands may contribute to Srsf3 KO prevention of Erbb2 breast cancer." (PMID 40568073, 2025). "Nevertheless, the function of SRSF3 in other types of breast cancer remains to be explored." (PMID 40568073, 2025). "Increased SRSF3 exon 4 exclusion correlates with poor survival in breast cancer patients." (PMID 34356101, 2021). "Elevated expression of SRSF3 (also referred to as SRp20) was documented to mediate a shift in the splicing profile of the MCL-1 gene to the exon 2-containing MCL-1l isoform, which encodes the antiapoptotic isoform in breast cancer cells." (PMID 29283381, 2017).
breast carcinoma (continued). "Together, these data clearly indicate that Srsf3 functions differently in the tissue context by altering the expression of specific sets of genes which could partially explain the different roles Srsf3 might play in the Erbb2 breast cancer from DEN-induced liver cancer." (PMID 40568073, 2025). "Thus, SRSF3 can promote the migration and invasion of breast cancer cells." (PMID 40129567, 2025). "In breast cancer, TDP-43 modulates the majority of splicing events via the serine/arginine-rich splicing factor 3 (SRSF3), thereby regulating the progression of triple-negative breast cancer." (PMID 38281298, 2024). "Two splicing factors, HnRNP H1 and SRSF3, involved in the regulation of splicing in highly spliced regions were found to be present in HER2-overexpressing breast cancers by RNA interference experiments." (PMID 36052258, 2022). "One study found that the SR proteins SRSF1, SRSF2, SRSF3, SRSF5 and SRSF6 are overexpressed in breast cancer." (PMID 36052258, 2022). "Among the SR proteins, SRSF1, SRSF2, SRSF3, SRSF5, and SRSF6 have been shown to be highly expressed in breast cancer." (PMID 31065692, 2019). "SRSF3 exon 4 inclusion was correlated with hnRNP L exon 7 inclusion in both HNSCC and breast cancer." (PMID 31828152, 2019). "Consistently with Erbb2 cancer tissues, knockdown of Srsf3 expression in mouse Erbb2+ NF639 cells and two human breast cancer cell lines ER+ MCF7 and HER2+ SKBR3 cells was also found to promote exon 11 inclusion of Eif4a2 and subsequently to inhibit the production of eIF4A2 protein." (PMID 40568073, 2025). "Comparing to Srsf3 WT liver cancer, Srsf3 KO significantly increases Sox4, E2f1, Trpv4, Trim6, and Myc expression, but does not so in Erbb2 breast cancer." (PMID 40568073, 2025). "To understand Srsf3-induced changes in RNA splicing, we performed alternative splicing analysis using rMATS and identified 1118 Srsf3-responsive splicing events in 899 genes in Erbb2 breast cancers with or without Srsf3 KO." (PMID 40568073, 2025). "Major Facilitator Superfamily Domain Containing 4A protein (Mfsd4a) involved in glucose transmembrane transport is on the top list of dysregulated genes, and is down-regulated 16-fold in Srsf3 KO Erbb2 breast cancer, but up-regulated 293-fold in DEN-induced Srsf3 KO liver cancer." (PMID 40568073, 2025). "Similarly, Htatip2 (Tip30), a tumor suppressor in various cancers, was downregulated in Erbb2 breast cancer, but upregulated in DEN-induced liver cancer following Srsf3 knockout." (PMID 40568073, 2025). "SRSF3 and HNRNPH1 regulate a splicing hotspot of HER2 in breast cancer cells." (PMID 34497807, 2021). "Furthermore, the roles of other SR proteins, including SRSF3, SRSF4 and SRSF6, have been shown in breast cancer." (PMID 32106418, 2020). "Moreover, the downregulation of SRSF3 by antisense oligonucleotides (ASO) was shown to sensitize oral squamous cell carcinoma and breast cancer cells to paclitaxel treatment." (PMID 32023846, 2020). "Additionally, among splicing regulators frequently altered in breast cancers (in >5% of tumors), we found different members of SR protein family (such as SRSF1, SRSF2, SRSF3, SRSF4, SRSF6, SRSF9, SRSF10, SRSF11) with at least one predicted binding motif in the CD44 v10 region." (PMID 33143085, 2020). "To find out whether other RBPs regulate translation initiation of specific mRNAs during tumor progression, we first analysed by immunohistochemistry (IHC) the expression of several RBPs (hnRNP A1, hnRNP H, RBM9/FOX2, SRSF1/ASF/SF2, SRSF2/SC35, SRSF3/SRp20, SRSF7/9G8) in breast cancers." (PMID 26930004, 2016). "Notably, overexpression of different SR proteins, such as SRSF3, was not able to alter the DCUN1D5 exon 4 splicing profile in breast cancer cells." (PMID 33918758, 2021).
colorectal cancer (24 papers, 2019 to 2025). A primary or metastatic malignant neoplasm that affects the colon or rectum. "Moreover, a short 130-aa peptide SRSP encoded by LOC90024 contributes to colorectal cancer development by promoting the binding of SRSF3 to Sp4 transcription factor." (PMID 37285335, 2023). "Moreover, recent studies have illustrated that lower expression of SRSF3 is associated with neoplasia progression and poor overall survival in the liver and colorectal cancer." (PMID 36293493, 2022). "This may also explain the fact that SRSF3 presents a high expression in normal colons, and the loss of SRSF3 expression is significantly correlated with low survival rate and short disease-free survival time, especially in the early step of colorectal cancer." (PMID 33072610, 2020). "Since the inhibition of SRSF3 was previously reported to induce apoptosis in other types of cancer cells such as glioblastoma, colorectal cancer and ovarian cancer, we also examined apoptotic markers in the SRSF3 knocked-down NSCLC cell lines." (PMID 40568080, 2025). "The SRSF3‐miR‐17‐92‐p21 pathway operates in colorectal cancer, linking SRSF3‐mediated pri‐miRNA processing and cancer pathogenesis." (PMID 37306233, 2023). "Then, we confirmed that SRSF3 was highly expressed in colorectal cancer (CRC) and was positively correlated with SRF." (PMID 35198444, 2022). "SRSF3 (Serine/arginine-rich splicing factor 3) is upregulated in various cancers, including breast, ovarian, retinoblastoma, gastric, hepatocellular, and colorectal cancer." (PMID 36344491, 2022). "In colorectal cancer, SRSF3 interacts with the small splice-regulating protein SRSP, mediating selective splicing of SP4 to produce cancerous SP4 subtypes, which leads to tumor occurrence and metastasis." (PMID 33854615, 2021). "Splicing factor SRSF3 is an oncogene and overexpressed in various kinds of cancers, however, the function and mechanism involved in colorectal cancer (CRC) remained unclear." (PMID 32308565, 2020). "Similar to colorectal cancer, the expression and function of SRSF3 are also contradictory in liver diseases." (PMID 33072610, 2020). "It was reported that SRSF3 and hnRNPA1 indicated the two highest increasing incidences (88 and 74%, respectively), for colorectal cancer." (PMID 33072610, 2020). "For example, studies have reported the antitumor activity of SFI003, a targeted inhibitor against SRSF3, in colorectal cancer, where SFI003 induced apoptosis in CRC cells through the SRSF3/DHCR24/ROS axis, and exhibited potent antitumor efficacy both in vitro and in vivo." (PMID 40129567, 2025). "Knockdown of SRSF3 expression significantly inhibits VEGF (vascular endothelial growth factor) expression in colorectal cancer cells, cancer cell migration, and tube formation by human umbilical vein endothelial cells (HUVECs) in vitro via a proangiogenic SRF (serum response factor) gene." (PMID 37416784, 2023). "SRSF3 is co-expressed with SRF in colorectal cancer tissues, and required for SRF expression." (PMID 37416784, 2023). "In contrast, knockdown of SRSF3 increases M1 protein level and thus, the ratio of M1 vs M2 protein levels, to induce the energy metabolic shift from glycolysis and oxidative phosphorylation in colorectal cancer cells." (PMID 37416784, 2023). "SRSF3 was reported to act as a tumor suppressor in hepatocellular carcinoma and colorectal cancer." (PMID 36293493, 2022). "As the modulation of serine/arginine-rich splicing factor 3 (SRSF3) may be therapeutically beneficial to colorectal cancer (CRC) treatment, the identification of novel SRSF3 inhibitors is highly anticipated." (PMID 35501301, 2022). "In addition, SRSF3 inhibits B7-H3 expression by regulating in its RNA splicing in colorectal cancer." (PMID 33461173, 2021). "SRSF3 exerts a powerful negative effect on the expression of the mutated in colorectal cancer (MCC) protein expression, which is significantly upregulated in various CRC cell lines." (PMID 33072610, 2020).